PGK1 (phosphoglycerate kinase 1)
Diseases named in the same sentence as PGK1 in open-access papers (continued):
Sharing a sentence is not in itself a finding about the gene and the disease.
Parkinson disease (17 papers, 2014 to 2025). A progressive degenerative disorder of the central nervous system characterized by loss of dopamine producing neurons in the substantia nigra and the presence of Lewy bodies in the substantia nigra and locus coeruleus. "PGK1 deficiency has been linked to early-onset parkinsonism, suggesting that glycolytic impairments contribute to the disease’s development and progression." (PMID 40681352, 2025). "PGK-1 deficiency, an X-linked recessive disorder, leads to various neurological disorders due to insufficient ATP regeneration, and early-onset parkinsonism has been occasionally reported as a complication of this condition." (PMID 39594624, 2024). "Neurologists and pediatricians should therefore look carefully for parkinsonism in not only PGK-1 deficiency patients but also carriers of this deficiency." (PMID 28649613, 2017). "This is the first report of parkinsonism developing in an otherwise asymptomatic carrier of a PGK-1 mutation." (PMID 28649613, 2017). "Here, we report a boy with PGK-1 deficiency and his mother, a carrier of a heterozygous mutation in PGK-1, both of whom presented with early-onset parkinsonism." (PMID 28649613, 2017). "Here, we describe a boy with PGK-1 deficiency and his mother, a heterozygous carrier of a PGK-1 mutation, both of whom presented with early-onset parkinsonism." (PMID 28649613, 2017). "Pgk1 has been reported deficient in Parkinsonism patients and may contribute to nigrostriatal damage." (PMID 39083243, 2025). "Pgk1 deficiency is accompanied by suffering from muscle lesions, motor neuron defect, neurological dysfunction and myopathy, as well as susceptibility to Parkinson’s disease." (PMID 31361595, 2019). "Based on this hypothesis, the penetrance of parkinsonism in PGK-1 deficiency is expected to be incomplete since variability in lyonization would lead to considerable variability in the severity of parkinsonism in female carriers." (PMID 28649613, 2017). "A 16-year-old boy with PGK-1 deficiency developed parkinsonism." (PMID 28649613, 2017). "Clinical and preclinical data have shown that increased Pgk1 activity and glycolysis ameliorate the neurodegeneration and progression of Parkinson’s disease." (PMID 38590360, 2024). "Phosphoglycerate kinase-1 (PGK-1), a crucial enzyme in the glycolytic pathway, has been implicated in early-onset parkinsonism." (PMID 39594624, 2024). "Extracellular PGK1 benefits the survival of dopaminergic neurons and decreases neurotoxin damage to alleviate Parkinson’s disease." (PMID 36749430, 2023). "Recent studies have shown that increasing glycolysis by PGK1 activation slows neurodegeneration in Parkinson’s disease." (PMID 33123536, 2020). "His mother, who exhibited normal PGK-1 activity in erythrocytes, developed parkinsonism at 36 years of age." (PMID 28649613, 2017). "Here, we report a boy with PGK-1 deficiency and his mother, a heterozygous carrier of a PGK-1mutation, both of whom presented with early-onset parkinsonism." (PMID 28649613, 2017). "PGK1 deficiency has been associated with parkinsonism, hereditary non-spherocytic hemolytic anemia, neurological impairment, and myopathy." (PMID 36749430, 2023). "Additionally, glycolysis plays a critical role in the treatment of Parkinson’s disease, and terazosin has been shown to activate the enzymatic activity of phosphoglycerate kinase 1 (PGK1)." (PMID 37881499, 2023). "Accordingly, proposed a strategy of improving glycolysis as a therapeutic target for Parkinson’s disease, by enhancing kinase activity of intracellular Pgk1 by Terazosin could promote energy production to delay the course of PD." (PMID 35456967, 2022). "Similarly, a 25-year-old male carrier of a PGK1 mutation that caused a marked decrease in PGK activity presented both exertional myoglobinuria and severe parkinsonism that was responsive to levodopa treatment." (PMID 33994936, 2021).
brain tumor (12 papers, 2017 to 2025). "Loss of function of PTEN in cancer increases autophosphorylation of phosphoglycerate kinase 1 (PGK1), enhancing glycolytic activity and promoting brain tumor formation." (PMID 38216787, 2024). "Similar results have been reported in brain tumours, indicating the crucial role of PGK1 in driving cancer initiation by regulating PTMs." (PMID 37723547, 2023). "PGK1 regulates metabolism (glycolysis), promotes cell proliferation in brain tumors and preferentially supports proliferation by functioning as a glycolytic enzyme in PDAC." (PMID 34650983, 2021). "PTEN inhibits glycolysis in brain tumour cells by directly interacting with phosphoglycerate kinase 1 (PGK1)." (PMID 33448640, 2020). "Same in brain tumour, hypoxia induced mTOR‐mediated PGK1 acetylation to induce autophagy." (PMID 40534132, 2025). "Inhibition of PGK1 autophosphorylation prevents glycolysis and brain tumour development." (PMID 37723547, 2023). "Under glutamate deprivation and hypoxic conditions, phosphoglycerate kinase 1 (PGK1) is acetylated at lysine 388 by NAA10/ARD1, which subsequently leads to the interaction of PGK1 with Beclin 1, causing phosphorylation of Beclin 1 at serine 30, thereby inducing autophagy and brain tumour formation." (PMID 39778006, 2025). "It has been described that PTEN establishes direct contact with the glycolytic enzyme phosphoglycerate kinase 1 (PGK1), dephosphorylating it and inhibiting its autophosphorylation; ultimately PTEN inhibits glycolysis, ATP production and brain tumour cell proliferation." (PMID 34588983, 2021). "Here we investigated whether ACF acts similarly in malignant glioma by monitoring the effects of ACF at the main HIF-1 downstream targets: PGK-1 and VEGF in both brain cancer cell lines and brain tumor lysate." (PMID 29097800, 2017). "In addition, the mitochondrial translocation of phosphoglycerate kinase 1 (PGK1) can also act as a protein kinase to activate PDK1 and inhibit the activity of PDH, thereby inhibiting the TCA cycle and eventually leading to the occurrence of brain tumours." (PMID 32928258, 2020).
neuroblastoma (11 papers, 2013 to 2025). Neuroblastoma (NB) is the most common solid, extracranial childhood tumor. "We have identified further hypoxia-associated prognostic factors for neuroblastoma including CXCR4, PGK1 and AQP1 leading to increased metastases." (PMID 35328549, 2022). "Remarkably, 3,5-di-O-caffeoylquinic acid is reported to possess neuroprotective effects by up-regulating phosphoglycerate kinase-1 in human neuroblastoma SH-SY5Y cells and senescence-accelerated prone mice." (PMID 31661844, 2019). "Han et colleagues demonstrated that CGA also has neuroprotective effects on Aβ-treated neuroblastoma SH-SY5Y cells through the upregulation of phosphoglycerate kinase-1 (PGK1) expression and the activation of ATP production." (PMID 31801234, 2019). "Our in vitro results suggest that in neuroblastoma cells CXCR4 in combination with overexpression of PGK1 also plays a role in cell proliferation." (PMID 24376734, 2013). "We next examined the relationship between PGK1 expression and survival of patients with neuroblastoma." (PMID 24376734, 2013). "Our data indicate that PGK1 plays an important role in neuroblastoma tumor growth and dissemination." (PMID 24376734, 2013). "The aim of the current study was to evaluate the role of PGK1 expression in neuroblastoma patients, to determine the impact of PGK1 expression levels on survival, and to correlate PGK1 expression with CXCR4 expression and bone marrow dissemination." (PMID 24376734, 2013). "PGK1 appears to play an important role for neuroblastoma, predicting survival and tumor dissemination." (PMID 24376734, 2013). "Immunocytochemistry, proliferation and expression analysis of CXCR4 and PGK1 were performed in neuroblastoma cell lines." (PMID 24376734, 2013). "Samples from 22 patients with neuroblastoma that were surgically treated at the University Medical Center Hamburg-Eppendorf were evaluated for expression of PGK1 and CXCR4 using immunohistochemistry." (PMID 24376734, 2013). "PGK1 is downregulated by inhibition of CXCR4 in neuroblastoma cells." (PMID 24376734, 2013). "Kelly and SH-EP Tet-21/N neuroblastoma cell lines were examined for expression of PGK1 and CXCR4." (PMID 24376734, 2013). "The expression of PGK1 is significantly associated with a negative impact on survival and tumor dissemination to the bone marrow in patients with neuroblastoma." (PMID 24376734, 2013). "This demonstrates the relevance of PGK1 also for neuroblastoma." (PMID 24376734, 2013). "PGK1 expression of the 22 neuroblastoma specimens was determined by immunohistochemistry." (PMID 24376734, 2013). "We report here, to our knowledge for the first time, the expression of PGK1 in neuroblastoma." (PMID 24376734, 2013). "The positive correlation of PGK1 with bone marrow metastases combined with the negative impact on survival we found in our study is an indicator that PGK1 might serve as an independent factor in the complex homing of neuroblastoma cells to the bone marrow." (PMID 24376734, 2013). "Similarly, high levels of N-MYC in N-MYC amplified neuroblastoma cells override HIF1α inhibition of cell cycle progression under hypoxia and cooperates with HIF1α to promote the expression of phosphoglycerate kinase 1 (PGK1), HK2, and LDHA." (PMID 33251216, 2020). "Moreover the expression of PGK1 is significantly associated with a negative impact on survival in patients with neuroblastoma." (PMID 24376734, 2013). "For instance, the chemical inhibitor CBR-470-1, which blocks PGK1 signalling, has been shown to protect SH-SY5Y neuroblastoma cells from neurotoxin MPP+ (1-methyl-4-phenylpyridinium ion)-induced cytotoxicity." (PMID 40055833, 2025). "We have previously investigated the roles of CAIX and PGK1, both enzymes that are controlled by HIF-1α and are up-regulated in the hypoxic microenvironment in neuroblastoma." (PMID 29865880, 2018).
neuroblastoma (continued). "PGK1 expression significantly positively correlates with CXCR4 expression, which is known to be an important player in the tumor biology of neuroblastoma, and tumor dissemination to the bone marrow." (PMID 24376734, 2013). "PGK1 expression positively correlates with CXCR4 expression in neuroblastoma patients and is downregulated by inhibition of CXCR4 in neuroblastoma cells." (PMID 24376734, 2013). "Moreover, hypoxia can significantly increase known adverse factors in neuroblastoma such as NMYC, CXCR4, PGK1 and AQP1, amongst others, leading to tumor progression and increased metastases." (PMID 35328549, 2022). "The positive correlation of PGK1 and CXCR4 expression in neuroblastoma patients as well as the downregulation of PGK1 through inhibition of the CXCR4 receptor, which we found in our in vitro studies, are indicators for a causal interaction between the PGK1 pathway and the CXCR4/SDF1 axis." (PMID 24376734, 2013). "Although the interaction of the CXCR4/SDF1-PGK1 axis to our knowledge has not been researched for neuroblastoma, PGK1 might be a possible therapeutic target also for this tumor entity." (PMID 24376734, 2013). "However, the role of PGK1 has not been investigated for neuroblastoma, and PGK1 might be a therapeutic target for this tumor entity." (PMID 24376734, 2013). "However, the role of PGK1 has not been investigated for neuroblastoma, and PGK1 could well be a novel therapeutic target for this tumor entity." (PMID 24376734, 2013).
pancreatic ductal adenocarcinoma (11 papers, 2017 to 2025). An infiltrating adenocarcinoma that arises from the epithelial cells of the pancreas. "Here, we demonstrate that phosphoglycerate kinase 1 (PGK1), a key ATP-producing glycolytic enzyme, plays a critical role in pancreatic ductal adenocarcinoma (PDAC) radioresistance." (PMID 41213904, 2025). "In pancreatic ductal adenocarcinoma, loss of SMAD4 induces the upregulation and nuclear translocation of the glycolytic enzyme PGK1, resulting in high oxidative phosphorylation and metastatic potential." (PMID 40139191, 2025). "NFAT5 facilitates pancreatic ductal adenocarcinoma cell survival by contributing to the Warburg effect through the transcription of PGK1." (PMID 39822413, 2024). "In pancreatic ductal adenocarcinoma (PDAC), circRREB1 increases PGK1 phosphorylation, enhancing glycolytic flux by disrupting the interaction between PTEN and PGK1." (PMID 39901896, 2025).
non-small cell lung carcinoma (10 papers, 2020 to 2025). A group of at least three distinct histological types of lung cancer, including non-small cell squamous cell carcinoma, adenocarcinoma, and large cell carcinoma. "For instance, high expression of PGK1 was significantly associated with poor prognosis in patients with non-small cell lung cancer." (PMID 39712033, 2024). "LINC00963 promotes non-small cell lung cancer metastasis by preventing ubiquitination of glycolytic kinase PGK1 (phosphoglycerate kinase 1), which activates the AKT/mTOR pathway." (PMID 32547948, 2020). "GBP1 promotes chemoresistance via PGK1-activated EMT signaling in non-small cell lung cancer." (PMID 34439200, 2021). "Other enzymes, such as PGI, PGK-1 and ENO-2, were found to be downregulated in an epidermal growth factor receptor (EGFR)-mutant non-small-cell lung cancer (NSCLC) with advanced resistance to EGFR tyrosine kinase inhibitors (TKIs), such as erlotinib." (PMID 39904372, 2025). "Two additional hallmarks of cancer metabolic reprogramming, ALDOA, and PGK1, were upregulated in keratinized OSCC, as indicated by increased glycolysis and metabolic reprogramming, which creates oncogenic stress, as suggested in other solid tumors, such as non-small cell lung cancer (NSCLC)." (PMID 32922662, 2020). "However, whether and how PGK1 affects non-small cell lung cancer (NSCLC) is not yet fully elucidated." (PMID 38163864, 2024).
osteosarcoma (10 papers, 2015 to 2025). A usually aggressive malignant bone-forming mesenchymal neoplasm, predominantly affecting adolescents and young adults. "The expression of methylated glycolytic enzymes such as HK2, GPI and PGK1 increased to promote glycolysis and osteosarcoma development." (PMID 37582735, 2023). "In parallel, YTHDF3—a reader protein for m6A—directly drives aerobic glycolysis in osteosarcoma cells while accelerating tumor proliferation by recognizing and stabilizing PGK1 mRNA at specific m6A sites; this key glycolytic enzyme plays a pivotal role in metabolism." (PMID 41019082, 2025). "In addition, RBM15 interacts with circ-CTNNB1 to enhance the expression of HK2, GPI and PGK1 in an m6A modification-dependent manner, leading to the promotion of the glycolytic process and the development of osteosarcoma." (PMID 37474926, 2023). "Afterwards, high expression of PGK1 can promote glycolysis and proliferation of osteosarcoma cells." (PMID 37582735, 2023). "In addition, the novel lncRNA HCG18 enhances aerobic glycolysis in osteosarcoma cells via miR-365a-3p/PGK1 signaling pathway regulation, which accelerating the development of osteosarcoma cells." (PMID 36618348, 2022). "Overexpression of HCG18 promotes osteosarcoma cell proliferation by augmenting aerobic glycolysis through regulation of the miR-365a-3p/PGK1 axis, suggesting that HCG18 may serve as a promising therapeutic target for osteosarcoma intervention." (PMID 40303288, 2025). "In osteosarcoma (OS), lncRNA HCG18 competes for miR-365a-3p with PGK1, which is a key glycolytic coding mRNA, and moderates the repressive effect of miR-365a-3p on PGK1, thereby resulting in increased PGK1 expression and aerobic glycolysis and promoting the proliferation of OS cells." (PMID 37723547, 2023). "Indeed, we observed that HIF-1 target genes ANGPTL4, VEGFA, GLUT1, PGK1 and HK2 were down-regulated at mRNA level when DEC2 is knocked down in several osteosarcoma cell lines, while the mRNA level of HIF-1α showed no obvious change by the DEC2 knockdown." (PMID 25884381, 2015).